GATA5 (GATA binding protein 5)
Diseases named in the same sentence as GATA5 in open-access papers (continued):
Sharing a sentence is not in itself a finding about the gene and the disease.
prostate carcinoma (4 papers, 2022 to 2023). A carcinoma that arises from epithelial cells of the prostate gland. "A study has found that GATA5 may be associated with the risk of prostate cancer through genome-wide association studies." (PMID 35565203, 2022). "Enrichment of the KEGG pathway was used to explore the mechanisms by which GATA5 affected the progression of prostate cancer." (PMID 35565203, 2022). "Overall, these findings demonstrated that GATA5 inhibits prostate cancer progression by regulating PLAGL2." (PMID 35565203, 2022). "Next, to further study the function of GATA5 in the growth of prostate cancer cells, serum-free medium containing pc-vector or pc-GATA5 DU145 cells was injected into the forelimb axilla of the mice." (PMID 35565203, 2022). "Our findings revealed that GATA5 was significantly under-expressed in prostate cancer by GEPIA and TCGA database analysis, which was consistent with our results in PCa samples and cells." (PMID 35565203, 2022). "High expression of GATA5 significantly retarded the progression of prostate cancer." (PMID 35565203, 2022). "Receiver operating characteristic curve (ROC) analysis showed that GATA5 distinguished prostate cancer with an area under the curve (AUC) of 0.76, indicating that GATA5 may contribute to the diagnosis of PCa." (PMID 35565203, 2022). "Furthermore, the mechanism by which GATA5 inhibits prostate cancer progression through regulating PLAGL2 via the FAK/PI3K/AKT pathway was also explored." (PMID 35565203, 2022). "In addition, we confirmed that GATA5 inhibited prostate cancer progression, including EMT, by regulating PLAGL2 via the FAK/PI3K/AKT pathway." (PMID 35565203, 2022). "Enrichment of KEGG pathway analysis was used to explore the specific mechanism by which GATA5 affects prostate cancer progression through the cBioPortal database, and the results showed that GATA5 may regulate prostate cancer progression through the FAK pathway." (PMID 35565203, 2022). "This drives the EHMT-mediated silencing of tumor suppressor genes such as forkhead Box O1 (FOXO1), GATA binding protein 5 (GATA5), and N-myc downstream regulated 1 (NDDRG1) in prostate cancer." (PMID 35740522, 2022).
endothelial dysfunction (3 papers, 2015 to 2025). In vascular diseases, endothelial dysfunction is a systemic pathological state of the endothelium (the inner lining of blood vessels) and can be broadly defined as an imbalance between vasodilating and vasoconstricting substances produced by (or acting on) the endothelium. "In contrast, there was significant alteration in the vasodilatory response to acetylcholine with a twofold increase in the effector concentration for half-maximum response in Gata5-null mesenteric arteries, indicative of endothelial dysfunction." (PMID 26617239, 2015). "It is therefore possible that endothelial dysfunction also affects Gata5-null mice renal arteries and blood flow, leading to decreased renal perfusion as observed in pharmacological and genetic models of NOS inhibition." (PMID 26617239, 2015). "In addition, the functional defect of GATA5 can aggravate oxidative stress and endothelial dysfunction by increasing the activity of ubiquitin-proteasome system, which is associated with instability of coronary and carotid plaques." (PMID 33684162, 2021). "This suggests that both endothelial dysfunction and kidney glomerular injuries in Gata5-null mice are not secondary to BP raise and are likely primary contributors to deregulated BP." (PMID 26617239, 2015).
myocardial infarction (3 papers, 2021 to 2025). Gross necrosis of the myocardium, as a result of interruption of the blood supply to the area, as in coronary thrombosis. "GATA5/ISL1 promotes this conversion by inhibiting Wnt/β-catenin signaling, ultimately improving cardiac structure and function in mice after myocardial infarction." (PMID 41403700, 2025). "Conversely, using CRISPRa to activate specific genetic programs in GATA5/ISL1+ fibroblasts promoted cardiac repair and improved function after myocardial infarction." (PMID 41403700, 2025).
ovarian carcinoma (3 papers, 2011 to 2022). A malignant neoplasm originating from the surface ovarian epithelium. "In addition to GATA5, the protein expressions of the other 6 family members in ovarian cancer are clearly displayed in the HPA database." (PMID 35488350, 2022).
renal cell carcinoma (3 papers, 2014 to 2025). "We recently found that tumor-specific hypermethylation of the GATA5 CpG island (CGI) occurs in renal cell carcinoma (RCC) and is associated with an adverse clinical outcome." (PMID 24533449, 2014). "Moreover, the association between GATA5 hypermethylation and both metastasis and progression-free survival suggests that epigenetic changes in GATA5 contribute to renal cell carcinoma development." (PMID 41514651, 2025). "Whether high-density CGI methylation of GATA3 or GATA5 is associated with the clinical course of patients with renal cell cancer (RCC) has not been clarified." (PMID 24549248, 2014).
Bicuspid aortic valve (2 papers, 2012 to 2013). The presence of an aortic valve with two instead of the normal three cusps (flaps). "The purpose of our study was to investigate the potential contribution of germline mutations in NOTCH1, GATA5 and TGFBR1 and TGFBR2 genes in a cohort of Italian patients with familial Bicuspid Aortic Valve (BAV)." (PMID 23578328, 2013). "This phenotype along with recent publications demonstrating bicuspid aortic valve and aortic valve stenosis in Gata5-null and Gata4;Gata5 compound heterozygote mice suggest that endocardial specific deficits of the G296S protein may contribute to the aortic and pulmonary valve stenosis." (PMID 22589735, 2012).
Diabetes (2 papers, 2014 to 2015). "Furthermore, pregestational diabetes increased ROS, impaired cell proliferation, and altered Gata4, Gata5 and Vegf-a expression in the fetal heart of diabetic offspring, which were all prevented by NAC treatment." (PMID 24533448, 2014).
dilated cardiomyopathy (2 papers, 2021 to 2022). Cardiomyopathy which is characterized by dilation and contractile dysfunction of the left and right ventricles. "As expected, heart GATA5 mRNA expression was significantly altered in association with various cardiovascular disease states the most significant being downregulated expression in association with dilated cardiomyopathy." (PMID 35548346, 2022). "GATA5 and GATA1 are closely related to cardiomyopathy diseases such as dilated cardiomyopathy, although their role in HCM has not yet been reported." (PMID 34054926, 2021).
fibrosis (2 papers, 2015 to 2023). the formation of excess fibrous connective tissue in an organ or tissue in a reparative or reactive process. "The older Gata5-null mice (on a regular salt diet) also developed cardiac perivascular fibrosis and several features of hypertensive nephropathy with increased proteinuria and decreased glomerular filtration rate." (PMID 26617239, 2015).
kidney cancer (2 papers, 2019 to 2022). Primary or metastatic malignant neoplasm involving the kidney. "In addition, decreased GATA5 mRNA is closely correlated with recurrence-free survival and may serve as a biomarker for prognostic evaluation in kidney cancer." (PMID 35565203, 2022). "In kidney cancer, GATA2, GATA3, GATA5 and GATA6 were mostly downregulated." (PMID 30872657, 2019).
lung adenocarcinoma (2 papers, 2021 to 2022). A carcinoma that arises from the lung and is characterized by the presence of malignant glandular epithelial cells. "And the suppressive effects of ARHGAP9 overexpression on proliferation, invasion and migration in lung adenocarcinoma were reversed by GATA5 silencing." (PMID 35040754, 2022). "To conclude, the present study successfully demonstrated for the first time that GATA5-induced ARHGAP9 upregulation has a protective effect on lung adenocarcinoma cells." (PMID 35040754, 2022). "More importantly, GATA5 silencing reversed the inhibitory effect of ARHGAP9 upregulation on the malignant progression of lung adenocarcinoma cells." (PMID 35040754, 2022). "Consistently, in this study, the genetic alteration rate of GATA5 was 10% in lung adenocarcinoma and the amplification accounted for most changes." (PMID 34093794, 2021). "According to the GEPIA database analysis, GATA5 and ARHGAP9 were found to be low expressed in lung adenocarcinoma, and they were positively correlated, and in addition ARHGAP9 low expression was associated with poor prognosis in lung adenocarcinoma." (PMID 35040754, 2022). "According to GEPIA database, GATA5 had a low expression in lung adenocarcinoma." (PMID 35040754, 2022). "Besides, it is noted that GATA5 was positively correlated with ARHGAP9 expression in lung adenocarcinoma." (PMID 35040754, 2022). "Thus, the present study was the first to suggest a protective effect of GATA5 induced ARHGAP9 on lung adenocarcinoma cells." (PMID 35040754, 2022). "Therefore, the present study focused on the effect of promoting GATA5 to induce ARHGAP9 on the malignant process of lung adenocarcinoma cells." (PMID 35040754, 2022). "Thus, the study successfully demonstrated that GATA5 could positively induce ARHGAP9 to inhibit lung adenocarcinoma cell progression." (PMID 35040754, 2022). "In this study, we discovered that GATA5 was downregulated in lung adenocarcinoma tissues and positively correlated with ARHGAP9 in lung adenocarcinoma." (PMID 35040754, 2022). "Whatʹs more, GATA5 silencing reversed the inhibitory effects of ARHGAP9 overexpression on the proliferation, invasion and migration in lung adenocarcinoma cells." (PMID 35040754, 2022). "Notably, regulation of GATA5 was found to directly affect the mRNA and protein expression of ARHGAP9 in lung adenocarcinoma cells." (PMID 35040754, 2022). "However, GATA5 downregulation had no relation with low overall survival rate of lung adenocarcinoma patients." (PMID 35040754, 2022).
lymph node metastases (2 papers, 2014 to 2023). "KIRC's pathological grades, clinical stages, and lymph node metastases were closely related to GATA2 and GATA5 levels." (PMID 36961416, 2023).
aneurysm (1 paper, 2023). Bulging or ballooning in an area of an artery secondary to arterial wall weakening. "Another BAV patient with aneurysm was carrying a heterozygous NOTCH1 variant (p.Thr123Met), which is considered as a polymorphism, and a heterozygous variant in the GATA5 gene (p.Leu233Pro), which has already been identified in one individual with BAV but without functional evidence." (PMID 36941270, 2023).
asthma (1 paper, 2023). "GATA5 associations have not been previously noted in asthma GWAS, although Gata5-deficient mice show airway hyperresponsiveness." (PMID 36914875, 2023).
benign prostatic hyperplasia (1 paper, 2023). A non-cancerous nodular enlargement of the prostate gland. "GATA5 encodes a transcription factor expressed in bronchial smooth muscle, bladder and prostate; a previous benign prostatic hyperplasia GWAS reported a GATA5 signal." (PMID 36914875, 2023).
breast tumors (1 paper, 2016).
chronic central serous chorioretinopathy (1 paper, 2025). "Recently, rs2379120 at the GATA5 gene was found to be associated with CVI in patients with chronic central serous chorioretinopathy and may have a role in choroidal vascularity." (PMID 39883627, 2025).
chronic gastritis (1 paper, 2019). Inflammation of the stomach that is chronic in nature. "However, chronic gastritis biopsies obtained from H. pylori-infected patients with hypermethylation of GATA5 promoter region showed downregulation of GATA5 gene expression." (PMID 30781778, 2019).
colorectal adenoma (1 paper, 2015). An adenoma that arises from the colon or rectum. "By contrast, GATA5 methylation has been reported as a suitable marker for early diagnosis of CRC and its methylation is observed in colorectal adenomas but not in inflammatory colorectal tissues." (PMID 26557847, 2015).
colorectal tumors (1 paper, 2014). "Although the sensitivities were different, the two studies indicated that the methylation of GATA5 in fecal DNA may present a potential biomarker for colorectal tumors." (PMID 25202404, 2014).
congenital heart defects (1 paper, 2025). "Herein, we performed genotypic–phenotypic analyses in two probands affected with novel GATA5 and GATA6 variants and congenital heart abnormalities, mostly affecting the right cardiac structures." (PMID 40076735, 2025).
Down syndrome (1 paper, 2019). "In a cohort of patients with Down syndrome and AVSD, variants with the highest probability of being damaging in cases compared to Down syndrome patients without cardiac defects were in the VEGF-A pathway genes COL6A1, COL6A2, CRELD1, FBLN2, FRZB, and GATA5." (PMID 31888141, 2019).
familial dilated cardiomyopathy (1 paper, 2022). A a genetic form of heart disease that occurs when heart (cardiac) muscle becomes thin and weakened in at least one chamber of the heart, causing the open area of the chamber to become enlarged (dilated). "Our data are consistent with the known link between GATA5 variants and multiple human cardiovascular pathologies including familial dilated cardiomyopathy and congenital ventricular-septal defects." (PMID 35548346, 2022).
gastric cardia adenocarcinoma (1 paper, 2011). A carcinoma that arises from glandular epithelial cells of the cardia of stomach. "Epigenetic Group 1, characterized by higher levels of GATA5 DNA methylation, consisted mainly of men with esophageal or gastric cardia adenocarcinomas." (PMID 22028801, 2011).
gastric cardia carcinoma (1 paper, 2011). A carcinoma that arises from epithelial cells of the cardia of stomach. "There were more males with esophageal and gastric cardia cancers in Cluster Group 1 characterized by higher GATA5 DNA methylation values (all p<0.05)." (PMID 22028801, 2011).
glioblastoma (1 paper, 2023). The most malignant astrocytic tumor (WHO grade IV). "Furthermore, the methylation of GATA5 (GATA binding protein 5) has been identified in 27.8% of glioblastoma patients and is strongly correlated with poor outcomes in primary glioblastoma cases." (PMID 37662954, 2023).
heart failure (1 paper, 2021). Inability of the heart to pump blood at an adequate rate to meet tissue metabolic requirements. "However, the functional defect of GATA5 will weaken the protective effect of AMPK on myocardial cells, and then affect the occurrence and development of CVDs such as heart failure and AMI." (PMID 33684162, 2021).
invasive breast carcinoma (1 paper, 2019). A carcinoma that infiltrates the breast parenchyma. "The promoter hypermethylation of GATA5 is believed to participate in invasive breast cancer development." (PMID 30872657, 2019).
liver cancer (1 paper, 2019). An epithelial or non-epithelial malignant neoplasm that arises from the liver. "To further demonstrate that enhancing the expression of GATA5 by expression vectors could suppress HCC cell proliferation, we transfected GATA5 expression vectors into the human liver cancer cell lines HLE, Bel 7402 and PLC/PRF/5." (PMID 30672133, 2019).
mesothelioma (1 paper, 2022). A usually malignant and aggressive neoplasm of the mesothelium which is often associated with exposure to asbestos. "HAND2 expression coincided with differential expression of the previously mesothelium- and mesothelioma-associated genes MSLN and WT1, as well as with GATA5 and MEIS2." (PMID 35354817, 2022).
oral cancer (1 paper, 2020). "IL-6 also induced promoter hypermethylation of several important TSGs, namely CHFR, GATA5, and PAX6, in oral cancer cells." (PMID 32678024, 2020).
papillary renal cell carcinoma (1 paper, 2014). A rare subtype of renal cell carcinoma, arising from the renal tubular epithelium and showing a papillary growth pattern, which typically manifests with hematuria, flank pain, palpable abdominal mass or nonspecific symptoms, such as fatigue, weight loss or fever. "Comparison of CGI methylation of GATA3 and GATA5 in ccRCC and papillary renal cell carcinoma showed significant statistical differences for the mean GATA3 (P=0.006) and GATA5 (P=0.015) relative methylation indices observed in both histological entities." (PMID 24549248, 2014).
periodontitis (1 paper, 2024). An acute or chronic inflammatory process that affects the tissues that surround and support the teeth. "Beyond its role in periodontitis, IL-6 induces oral carcinogenesis by promoting the hypermethylation of tumor suppressor genes, such as CHFR, GATA5, and PAX6." (PMID 38612423, 2024).
prostate tumors (1 paper, 2024). "GATA5 was further downregulated in prostate tumors compared to adjacent non-tumor tissues of AA men (P < 0.001)." (PMID 38566104, 2024). "Conversely, GATA5 and GATA6 gene expression were negatively correlated with DNA methylation at specific loci in prostate tumors and adjacent non-tumor tissues regardless of race (left panel: left bottom quadrant)." (PMID 38566104, 2024).
renal carcinoma (1 paper, 2014). A carcinoma arising from the epithelium of the renal parenchyma or the renal pelvis. "Similarly, GATA5 CGI methylation was not detectable or was low in normal primary cells but demonstrated higher relative methylation indices only for 4/6 renal cancer cell lines." (PMID 24549248, 2014).
squamous cell lung carcinoma (1 paper, 2021). A carcinoma arising from squamous bronchial epithelial cells. "And in squamous cell lung carcinoma, the increased GATA5/6 also indicated better survival probability." (PMID 34093794, 2021).
thoracic aortic aneurysm (1 paper, 2025). An aneurysm formed in the wall of the proximal portion of the descending aorta proceeding from the arch of the aorta. "Mutations in genes such as NOTCH1, GATA5, and ACTA2 have been implicated in the pathogenesis of both BAV and thoracic aortic aneurysms, suggesting shared genetic etiologies." (PMID 40110250, 2025).